IGF2BP2 (insulin like growth factor 2 mRNA binding protein 2)
Diseases named in the same sentence as IGF2BP2 in open-access papers (continued):
Sharing a sentence is not in itself a finding about the gene and the disease.
triple-negative breast carcinoma (10 papers, 2021 to 2025). An invasive breast carcinoma which is negative for expression of estrogen receptor (ER), progesterone receptor (PR), and human epidermal growth factor receptor 2 (HER2). "Single nucleotide polymorphism variants in the IGF2BP2 gene have been associated with the incidence of breast cancer, including triple negative breast cancer (TNBC), with higher IMP2 protein expression consistent with an oncogenic role." (PMID 40141058, 2025). "In triple-negative breast cancer, high IGF2BP2 expression is associated with cancer cell migration and invasion and promotes the stability of MYC mRNA." (PMID 35915142, 2022). "IGF2BP2 has been suggested as one of the major RBPs which helped form the upper stream regulatory elements of several hub circRNAs in triple-negative breast cancers." (PMID 34774079, 2021). "To evaluate the translational potential of IGF2BP2 as a cancer treatment target, we examined the expression of IGF2BP2 in patient samples available in TCGA and found that it is significantly overexpressed in multiple cancers, including triple-negative breast cancer (TNBC)." (PMID 40347943, 2025). "Moreover, the depletion of circCD44 or IGF2BP2 affects the levels of m6A-modified c-MYC mRNA, suggesting that the interaction between circCD44 and IGF2BP2 may stabilize c-MYC in triple-negative breast cancer (TNBC)." (PMID 39596216, 2024). "For example, in triple-negative breast cancer (TNBC), IGF2BP2 enhances cell proliferation and facilitates the G1/S phase transition by directly regulating CDK6 in an m6A-dependent manner and recruiting EIF4A1 to promote CDK6 translation output." (PMID 39596216, 2024). "From all the RBPs investigated, seven were differentially expressed and upregulated (AGO2, EIF4A3, ELAVL1, IGF2BP2/3, LIN28B, and U2AF2), showing that these genes have an important role in triple-negative breast cancer development." (PMID 35805051, 2022). "IGF2BP2 and IGF2BP3 synergistically promote the metastasis of triple-negative breast cancer by promoting the inactivation of progesterone receptors." (PMID 33550985, 2021).
esophageal adenocarcinoma (9 papers, 2016 to 2023). A malignant tumor with glandular differentiation arising predominantly from Barrett mucosa in the lower third of the esophagus. "Elsewhere, IGF2BP2 polymorphism has been found to increase the risk of developing human esophageal adenocarcinoma and Barret’s esophageal tissue." (PMID 33568150, 2021). "In a study on esophageal adenocarcinoma, IGF2BP2 was found to be more expressed in metastatic lesions than in primary tumors." (PMID 36793593, 2023). "Consistently, high IGF2BP2 expression in esophageal adenocarcinoma was found in another independent study, particularly in tumors of increased size and in metastatic lesions, suggesting the potential prognostic value of this protein." (PMID 29736175, 2018). "Interestingly, in the study of esophageal adenocarcinoma, IGF2BP2 was found to be more highly expressed in metastatic lesions than in primary tumors." (PMID 32391379, 2020). "Although IGF2BP2 has been shown in the literature to be highly expressed in high-grade dysplasia (HGD) or Barrett’s esophagus, which are considered to be precancerous lesions of EC, it is unknown whether the targeted peptide can be used for the diagnosis of precancerous lesions." (PMID 36364436, 2022). "Thirdly, the tumor tissues and cell lines we obtained were all esophageal squamous carcinoma, and expression of IGF2BP2 on esophageal adenocarcinoma was not performed in our study, although some studies have demonstrated that IGF2BP2 is also highly expressed in adenocarcinoma." (PMID 36364436, 2022).
liver fibrosis (9 papers, 2022 to 2025). "The expression of IGF2BP2 has been linked to liver fibrosis, T2DM, and cancer." (PMID 39771098, 2024). "IGF2BP2 promotes liver fibrosis progression by increasing aldolase A (ALDOA) expression and overall lactylation levels." (PMID 40421024, 2025). "The m6A-binding protein IGF2BP2 exhibits increased expression in liver fibrosis and activated HSCs and correlates with poor prognosis." (PMID 40421024, 2025). "Although it represents potential, however, the suitability of IGF2BP2 as a therapeutic target for different etiologies of liver fibrosis requires further validation." (PMID 38443347, 2024). "In conclusion, our findings reveal the essential role of IGF2BP2 in liver fibrosis by regulating glycolytic metabolism and highlight the potential of targeting IGF2BP2 as a therapeutic for liver fibrosis." (PMID 38443347, 2024). "Subsequently, we employed CCl4 to induce liver fibrosis in mice, with the aim of investigating the expression of IGF2BP2 in fibrotic liver tissues." (PMID 38443347, 2024). "Through the analysis of the GSE55747 dataset, we observed an increased expression of Igf2bp2 in liver fibrosis induced by CCl4." (PMID 38443347, 2024). "Here, we observed that IGF2BP2 is highly expressed in liver fibrosis and activated hepatic stellate cells (HSCs), and inhibition of IGF2BP2 protects against HSCs activation and liver fibrogenesis." (PMID 38443347, 2024). "Given the significant involvement of HSCs activation in the development of liver fibrosis, our subsequent inquiry focused on examining the expression profile of IGF2BP2 in activated HSCs and its impact on the activation of these cells." (PMID 38443347, 2024). "Our findings indicate that IGF2BP2 is upregulated in liver fibrosis, and silencing IGF2BP2 protects against carbon tetrachloride (CCl4)-induced liver fibrosis." (PMID 38443347, 2024). "Accumulating evidence suggests that IGF2BP2 plays a significant role in various liver diseases, such as nonalcoholic steatohepatitis, fatty liver, hepatic steatosis, liver fibrosis, and liver cirrhosis." (PMID 38443347, 2024). "This work shows that IGF2BP2, a newly identified m6A reader, is upregulated in liver fibrosis and activated HSCs." (PMID 38443347, 2024). "Another study showed that IGF2BP2 knockdown effectively inhibited CCl4-induced liver fibrosis, which is consistent with our data." (PMID 38443347, 2024). "In conclusion, the results of this study suggest that the suppression of IGF2BP2 expression in the liver can mitigate the advancement of liver fibrosis." (PMID 38443347, 2024). "The preceding data indicates IGF2BP2 potential involvement in the development of liver fibrosis." (PMID 38443347, 2024). "It is unclear whether IGF2BP2-mediated glycolytic metabolism plays a central role in the process of liver fibrosis or is the result of joint involvement with other glycolytic genes." (PMID 38443347, 2024). "Besides, Sirius red and Masson staining showed that liver fibrosis was developed in Ad-Igf2bp2-infected mice." (PMID 39872354, 2022). "In conclusion, our study reveals the essential role of IGF2BP2 as an m6A-binding protein in the pathogenesis of liver fibrosis through the regulation of glycolytic metabolism and extends the potential role of lactylation in the activation of HSCs and liver fibrosis." (PMID 38443347, 2024). "However, the impact of IGF2BP2-mediated metabolic changes on liver fibrosis remains uncertain." (PMID 38443347, 2024). "Therefore, targeting IGF2BP2 may hold promise as a potential therapeutic strategy for the treatment of liver fibrosis." (PMID 38443347, 2024). "Importantly, our study highlights that targeting IGF2BP2 could be an effective strategy for anti-liver fibrosis therapy." (PMID 38443347, 2024). "IGF2BP2 increases the level of H3K18la by promoting the expression of the sugar metabolism-related gene ALDOA, thereby promoting liver fibrosis." (PMID 41199784, 2025). "Notably, mice lacking IGF2BP2 were protected from liver fibrosis in vivo." (PMID 38443347, 2024).
lymph node metastasis (8 papers, 2020 to 2026). "High IGF2BP2 expression was significantly linked to lymph node metastases, disease stage, and the survival of human patients with OSCC (p=0.004, p=0.027, p=0.038, and p=0.011, respectively)." (PMID 35919812, 2022). "Our data also indicated that advanced clinical stage, development of large tumor, and progression of lymph node metastasis were associated with the IGF2BP2 rs1470579 AC+CC genotype." (PMID 32784624, 2020). "Statistical analysis revealed that IGF2BP2 expression was consistent with the degree of malignancy (i.e., tumor size, lymph node metastasis, and stage)." (PMID 37088822, 2023). "Univariate and multivariate analyses both identified IGF2BP2 expression, histological grade, T status, lymph node metastases, and disease stage as key independent prognostic factors impacting the overall survival of OSCC patients." (PMID 35919812, 2022). "Our results showed that IGF2BP2 cytoplasmic protein expression was significantly correlated with lymph node metastasis, cancer stage, and patient survival." (PMID 35919812, 2022). "In conclusion, our findings demonstrate that IGF2BP2 protein expression is prevalent in OSCC tissues, and that protein expression levels were associated with histological grade, T status, lymph node metastasis, disease stage, and survival." (PMID 35919812, 2022). "Through the forest plot analysis, there are statistically significant linkages between gender (p = 0.019), distant metastasis (p = 0.022), neck lymph node metastasis (p = 0.002), the expression of IGF2BP2 (p = 0.025) and the outcome of HNSCC patients." (PMID 32391379, 2020). "Moreover, multivariate cox proportional hazard models revealed that cytoplasmic IGF2BP2 expression, T status, and lymph node metastasis were independent prognostic factors for survival." (PMID 35919812, 2022). "And the correlation between IGF2BP2 expression and lymph node metastasis, TNM stage was not statistically significant although there was a certain trend." (PMID 37983610, 2024). "Although our analysis of IGF2BP2 expression does not effectively predict disease-free survival (data not shown), it is closely related to the locally advanced neck and lymph node metastasis in HNSCC patients." (PMID 32391379, 2020).
oral cancer (8 papers, 2020 to 2025). "In conclusion, our results suggest that IGF2BP2 polymorphisms are associated with less favorable oral cancer clinical characteristics." (PMID 32784624, 2020). "In summary, our study investigated the occurrence of the IGF2BP2 polymorphism in Taiwanese patients with oral cancer." (PMID 32784624, 2020). "Here, through conducting a transcriptome analysis, we demonstrated that expression of epiregulin (encoded by the EREG gene) was positively regulated by IGF2BP2, accompanied by increases in levels of several epithelial-mesenchymal transition genes and oral cancer migration." (PMID 38250159, 2024). "In addition, previous study also found that IGF2BP2 polymorphisms were associated with less favorable oral cancer clinical characteristics." (PMID 36281789, 2022). "The IGF2BP2 rs4402960 and rs1470579 polymorphisms are both located in the intron region, which might influence the risk of oral cancer through IGF2BP2 gene post-transcription mechanisms." (PMID 32784624, 2020). "Additionally, we examined the association between the clinical parameters of patients with oral cancer and the IGF2BP2 rs11705701, rs4402960, and rs1470579 polymorphisms." (PMID 32784624, 2020). "The results indicate that the male patients with oral cancer and with the rs11705701 GA+AA, rs4402960 GT+TT, and rs1470579 AC+CC genotypes had increased risk of advanced clinical stage, larger tumor, and progression of lymph node metastasis compared with those with wild-type IGF2BP2." (PMID 32784624, 2020). "Our data provide new mechanistic insights into the tumor-promotive features of IGF2BP2, on the management of patients with oral cancer." (PMID 38250159, 2024). "Yet, as N6-methyladenosine modification of various RNA species has been implicated in regulating many aspects of OSCC biology 21-23, the involvement of IGF2BP2 in influencing oral cancer progression remains largely unclear." (PMID 38250159, 2024). "However, the association between the IGF2BP2 polymorphism and oral cancer risk remains unclear." (PMID 32784624, 2020). "Collectively, these findings suggest that EREG, serving as a functional mediator of IGF2BP2-regulated EMT and cell invasion in oral cancer, may be implicated as a potential target for antimetastatic therapies." (PMID 38250159, 2024). "As small molecules targeting IGF2BP2 for cancer therapy have been developed 34, our results may offer potential avenues for the management of oral cancer." (PMID 38250159, 2024). "One concern is that, although we demonstrated promotion of OSCC migration and invasion by manipulation of IGF2BP2 levels in in vitro experiments, the effects of this RNA-binding protein on oral cancer progression may be different within complex tumor microenvironments in in vivo settings." (PMID 38250159, 2024).
osteosarcoma (8 papers, 2021 to 2025). A usually aggressive malignant bone-forming mesenchymal neoplasm, predominantly affecting adolescents and young adults. "In contrast, IGF2BP2 was found to be a risk gene for osteosarcoma, and high expression of IGF2BP2 inhibited survival in patients with osteosarcoma." (PMID 33952279, 2021). "We demonstrated that IGF2BP2 was a risk gene for osteosarcoma, and high expression of IGF2BP2 was associated with poor survival in patients with osteosarcoma." (PMID 33952279, 2021). "Therefore, we selected two m6A methylation regulators (FTO and IGF2BP2) using univariate Cox proportional risk regression model to explore their prognostic value in osteosarcoma and establish gene signature." (PMID 33952279, 2021). "Among the m6A methylation regulators, the abnormal expression of FTO and IGF2BP2 was found to be significantly associated with the progression of osteosarcoma and is considered to be the key factors that can independently predict the prognosis of patients with osteosarcoma." (PMID 33952279, 2021). "In osteosarcoma, IGF2BP2 interacts with m6A motifs within the CDS of MN1, promoting both mRNA stability and translation." (PMID 39596216, 2024). "The detailed analysis confirmed the important role of IGF2BP2 in the survival of patients with osteosarcoma." (PMID 33952279, 2021). "In addition, METTL14-mediated MN1 methylation raises the stability and translation of MN1 transcript through the IGF2BP2-dependent pathway, prompting all-trans-retinoic acid resistance and progression in osteosarcoma." (PMID 37280679, 2023). "The genes DDX24, DDX21, WARS, and IGF2BP2 might play a pivotal role in osteosarcoma, and these genes will be considered as therapeutic targets for osteosarcoma treatment." (PMID 36140189, 2022).
clear cell renal cell carcinoma (7 papers, 2022 to 2025). "For instance, in clear cell renal cell carcinoma (ccRCC), IGF2BP2 stabilizes salt-inducible kinase 2 (SIK2) mRNA via FTO-mediated m6A modification, enhancing autophagic flux and reducing ccRCC growth and metastasis." (PMID 39596216, 2024). "For instance, circ-TNPO3 bound to IGF2BP2, resulting in destabilization of SERPINH1 mRNA in clear cell renal cell carcinoma." (PMID 40883266, 2025). "In clear cell renal cell carcinoma, SIK2 downregulation promotes tumor progression by inhibiting autophagy, depending on FTO/IGF2BP2-m6A axis-mediated SIK2 mRNA stabilization." (PMID 37280679, 2023). "A similar functional mechanism was founded in clear cell renal cell carcinoma, suggesting that circTNPO3 might downregulate the stability of SERPINH1 mRNA, a type of oncogene, by competitively binding to IGF2BP2." (PMID 40822457, 2025).
endometrial cancer (7 papers, 2018 to 2026). Primary or metastatic malignant neoplasm involving the endometrium (mucous membrane that lines the endometrial cavity). "However, the mechanism underlying the regulatory effects of circRNAs on endometrial cancer progression via IGF2BP2 remains unknown." (PMID 38778089, 2024). "IGF2BP2, which was the most down-regulated gene in CTCF-altered endometrial cancer, was identified as a candidate tumour suppressor gene in a pan-cancer screen for homozygously deleted genes." (PMID 30513694, 2018).
esophageal cancer (7 papers, 2021 to 2025). A primary or metastatic malignant neoplasm involving the esophagus. "Elevated IGF2BP2 expression in esophageal cancer tissues correlates with aggressive tumor behavior, as IGF2BP2 overexpression potentiates stem-like traits in cancer cells." (PMID 40986143, 2025). "The esophageal cancer cell lines exhibited varying degrees of IGF2BP2 overexpression, with KYSE-30 expression being the highest among all the displayed esophageal cancer cells." (PMID 36364436, 2022). "It is known IGF2BP2 is highly expressed and induces progression in multiple malignancies, including esophageal cancer." (PMID 35971159, 2022). "In this study, we aim to identify a peptide-targeting IGF2BP2 that specifically binds to human ESCC for near-infrared imaging of esophageal cancer." (PMID 36364436, 2022). "In our study, we found that the positive rate of IGF2BP2 in esophageal cancer tissue was up to 96.9%, implying that IGF2BP2 may be somehow involved in ESCC tumorigenesis." (PMID 36364436, 2022). "IGF2BP2 also promotes metabolism of esophageal cancer and HNSCC." (PMID 33568150, 2021).
fatty liver (7 papers, 2019 to 2024). "Histology analysis showed that long-term HFHC diet feeding-associated hepatic steatosis was substantially reduced in IGF2BP2-deficient mouse livers." (PMID 39872354, 2022). "However, IGF2BP2-deficient mice show remarkable resistance to the diet-induced fatty liver via enhancing the expression of mRNAs encoding mitochondrial proteins, such as uncoupling protein-1 (UCP1)." (PMID 37020540, 2023). "Adenovirus or adeno-associated virus-mediated overexpression of IGF2BP2 could induce liver steatosis, inflammation, and fibrosis in mice, at least in part, by increasing Tab2 mRNA stability." (PMID 39872354, 2022). "In agreement with the observations in the HFHC mice, knockdown of IGF2BP2 also substantially ameliorate hepatic steatosis, liver inflammation, and fibrosis in MCD diet-induced NASH mice." (PMID 39872354, 2022). "Histology analysis showed that Ad-Igf2bp2-infected mice developed hepatic steatosis as shown by H&E and Oil Red O staining." (PMID 39872354, 2022). "In addition, it has been shown that inhibition of IGF2BP2 protects against diet-induced hepatic steatosis." (PMID 38443347, 2024). "HFD-fed hepatocellular specific IGF2BP2 knockout mice have been found to exhibit reduced liver fatty acid oxidation, increased triglyceride accumulation, and moderate fatty liver disease, possibly due to significantly reduced expression levels of the CPT1A and PPARα." (PMID 37020540, 2023). "Global deletion of the mRNA-binding protein insulin-like growth factor 2 mRNA-binding protein 2 (IGF2BP2 or IMP2) in mice causes resistance to obesity and fatty liver induced by a high-fat diet (HFD), whereas liver-specific IMP2 overexpression results in steatosis." (PMID 31209109, 2019). "A recent study showed that IGF2BP2 could promote liver steatosis by enhancing PPARγ mRNA stability." (PMID 39872354, 2022).